ZNF678 (zinc finger protein 678)
Description:
May be involved in transcriptional regulation.
Synonyms: MGC42493
Tractability: PROTAC: ubiquitination databases record sites on it.
Gene: Protein-coding gene on chromosome 1 (227,563,543 to 227,677,443, forward strand). Ensembl gene ENSG00000181450.
Subcellular location: Nucleus
Subcellular location (Human Protein Atlas): Nucleoli; Cytosol; Nucleoplasm
Pathways (Reactome):
Gene expression (Transcription): Generic Transcription Pathway
Gene Ontology:
Molecular function: DNA-binding transcription factor activity, RNA polymerase II-specific; RNA polymerase II cis-regulatory region sequence-specific DNA binding
Biological process: regulation of DNA-templated transcription; negative regulation of transcription by RNA polymerase II
Cellular component: nucleus
Genetic constraint (gnomAD): Loss-of-function variants: 5 observed, 3.6 expected, observed/expected ratio (o/e) 1.39, 90% interval 0.67 to 1.92. That is too few expected variants to judge how well the gene tolerates losing a copy. Missense variants: 593 observed, 615.78 expected, observed/expected ratio (o/e) 0.96, 90% interval 0.9 to 1.03. Synonymous variants: 218 observed, 201.06 expected, observed/expected ratio (o/e) 1.08, 90% interval 0.97 to 1.21.
Homologues: Orthologues: chimpanzee ZNF678 (99% identical), mouse Zfp738 (51% identical), mouse Zfp457 (48% identical), mouse Zfp595 (48% identical), rat AABR07009105.1 (38% identical), mouse Zfp953 (25% identical). Paralogues in human: ZNF681 (59% identical), ZNF724 (59% identical), ZNF85 (59% identical), ZNF708 (55% identical), ZNF726 (54% identical), ZNF254 (53% identical), ZNF595 (53% identical), ZNF728 (53% identical), ZNF676 (52% identical), ZNF429 (52% identical), ZNF43 (51% identical), ZNF93 (51% identical), and 164 more.
Diseases named in the same sentence as ZNF678 in open-access papers:
ZNF678 is named in the same sentence as 4 diseases in open-access papers, as found by Europe PMC text mining. Sharing a sentence is not in itself a finding about the gene and the disease. The quoted sentences say what the papers report.
Azoospermia (1 paper, 2021). Absence of any measurable level of sperm,whereby spermatozoa cannot be observed even after centrifugation of the semen pellet. "The authors also observed that ZNF676 is co-expressed with the ZNF678 gene, where lies a risk locus for azoospermia." (PMID 33921254, 2021).
tumor (2 papers, 2022 to 2025). "In the 20 pairs of clinical samples we collected, rt-PCR results showed that ZNF678, ARID1A, XIAP, MIS18BP1, and MBTPS2 were highly expressed in tumor tissues." (PMID 36249009, 2022).
infectious disease (1 paper, 2023). A disorder directly resulting from the presence and activity of a microbial, viral, or parasitic agent in humans. "Conversely, the remaining three genes carrying homozygous missense variants in the twins–SLC17A9, ZNF678 and ACP5 –had no known link to infectious diseases." (PMID 36972292, 2023).
ZNF678 also shares sentences with these, for which no sentence is quoted: cancer (1 paper).